CA13 (carbonic anhydrase 13)
Description:
Catalyzes the reversible conversion of carbon dioxide to hydrogencarbonate/bicarbonate and thus is essential in the regulation of pH and metabolic processes.
Synonyms: CAXIII; FLJ37995; MGC59868
Tractability: Small molecule: an approved drug acts on it; a structure with a bound ligand is known; a high-quality ligand is known; it belongs to a druggable protein family. PROTAC: a small molecule that binds it is known.
Target class: Enzyme; Lyase
Gene: Protein-coding gene on chromosome 8 (85,220,587 to 85,284,073, forward strand). Ensembl gene ENSG00000185015.
Subcellular location: Cytoplasm, cytosol
Subcellular location (Human Protein Atlas): Nucleoli; Nucleoplasm; Vesicles
Pathways (Reactome):
Metabolism: Reversible hydration of carbon dioxide
Gene Ontology:
Molecular function: protein binding; carbonate dehydratase activity; zinc ion binding
Cellular component: cytoplasm; cytosol; myelin sheath
Genetic constraint (gnomAD): Loss-of-function variants: 14 observed, 25.58 expected, observed/expected ratio (o/e) 0.55, 90% interval 0.36 to 0.86. The upper end of that interval is the gene's LOEUF score, 0.86, which puts it in group 3 of 6, group 1 being the genes least tolerant of losing a copy. Missense variants: 285 observed, 296.2 expected, observed/expected ratio (o/e) 0.96, 90% interval 0.87 to 1.06. Synonymous variants: 110 observed, 106.65 expected, observed/expected ratio (o/e) 1.03, 90% interval 0.88 to 1.21.
Homologues: Orthologues: chimpanzee CA13 (99% identical), macaque CA13 (96% identical), guinea pig CA13 (92% identical), rat Car13 (92% identical), mouse Car13 (91% identical), dog CA13 (90% identical), pig CA13 (89% identical), rabbit CA13 (82% identical), tropical clawed frog ca3 (63% identical), zebrafish ca2 (62% identical), zebrafish cahz (62% identical), Caenorhabditis elegans cah-5 (39% identical), and 13 more. Paralogues in human: CA2 (60% identical), CA1 (60% identical), CA3 (58% identical), CA7 (53% identical), CA5B (49% identical), CA5A (47% identical), CA8 (39% identical), CA14 (37% identical), CA12 (36% identical), CA9 (34% identical), CA6 (33% identical), CA10 (33% identical), and 2 more.
Diseases named in the same sentence as CA13 in open-access papers:
CA13 is named in the same sentence as 10 diseases in open-access papers, as found by Europe PMC text mining. Sharing a sentence is not in itself a finding about the gene and the disease. The quoted sentences say what the papers report.
colorectal cancer (3 papers, 2005 to 2025). A primary or metastatic malignant neoplasm that affects the colon or rectum. "Interestingly, an increase in IBD/IBS was also observed for CA13 (carbonic anhydrase XIII), protein associated with colorectal cancer (CRC), as well as SNAP23 (synaptosomal-associated protein 23) and NADK (NAD kinase) which are linked to insulin signalling and type 2 diabetes mellitus (T2DM)." (PMID 40481885, 2025). "Nonetheless, the downregulation of cytosolic CA I, II and XIII in colorectal cancer may result from reduced levels of a common transcription factor or loss of the closely linked CA1, CA2 and CA13 alleles on chromosome 8." (PMID 29495652, 2018). "The down-regulation of cytosolic CA I, II and XIII in colorectal cancer may result from reduced levels of a common transcription factor or loss of closely linked CA1, CA2 and CA13 alleles on chromosome 8." (PMID 15836783, 2005).
breast carcinoma (2 papers, 2023). "Our data shows that the proteins with the highest fold change in breast cancer were carbonic anhydrase 13 (CA13), sulfatase-modifying factor 2 (SUMF2), and synaptosomal-associated protein 23 (SNAP23)." (PMID 37064098, 2023). "Whereas it is likely that patients with Basal-like breast cancer could benefit from CA9- and CA13-targeted therapy, our current findings show that patients with HER2-enriched breast cancer will likely follow a more severe disease trajectory if treated with a carbonic anhydrase inhibitor." (PMID 37098526, 2023).
CA13 also shares sentences with these, for which no sentence is quoted: tumor (2 papers); astrocytoma (1); cancer (1); colorectal tumors (1); connective tissue diseases (1); depression (1); interstitial lung disease (1); type 2 diabetes mellitus (1).